PLA2G2A (phospholipase A2 group IIA)
Diseases named in the same sentence as PLA2G2A in open-access papers (continued):
Sharing a sentence is not in itself a finding about the gene and the disease.
cancer (46 papers, 2004 to 2025). A tumor composed of atypical neoplastic, often pleomorphic cells that invade other tissues. "PLA2G2A has been associated with poor survival in various cancers and has been implicated in the recruitment of immune cells." (PMID 39009587, 2024). "The product of the PLA2G2A gene promotes prostaglandin E2 synthesis that stimulates Wnt signaling and has been identified as a susceptibility gene for cancers of the small and large intestine." (PMID 36142758, 2022). "Significantly down-regulated genes in cancer tissue, compared to normal tissue included PLA2G2A, MUC4, PCK1, TXNIP, and genes encoding the CCR7 ligands, CCL19 and CCL21, which are lymphoid chemokines involved in the chemotaxis of lymphoid cells such as leukocytes and dendritic cells." (PMID 38505585, 2024). "Although tanshinone I might have multiple targets in the cells, its ability to inhibit PLA2G2A and suppress K-ras-driven cancer proliferation provides a possibility for use in treatment of cancers with K-ras mutations." (PMID 36233022, 2022). "And PLA2G2A was found to be associated with different disease states including cancer." (PMID 34051738, 2021). "Pla2g2a–/– mice had lower levels of ROS-related metabolites, including α-aminoadipate, 3-indoxyl sulfate, methionine sulfoxide, and branched-chain amino acids, which could be associated with altered systemic responses including inflammation and cancer." (PMID 35076024, 2022). "Little is known about the role of Pla2g2a in skeletal muscle in cancer; however, it is known to hydrolyse fatty acids from phospholipids." (PMID 41243421, 2025). "The IDEGs (SLPI, IAPP, NPY, ISG15, PLA2G2A, and HLA-DMB) in the predictive PCa risk model constructed in the present study play an important regulatory role in cancer." (PMID 36774376, 2023). "All listed sPLA2 undergo increased expression only in certain types of cancer (apart from GBM): PLA2G2A (in 2); PLA2G5 (in 1); PLA2G12A (in 4); PLA2G15 (in 3)." (PMID 36765904, 2023). "PLA2G2A is suggested to be secreted from cancer cells, eliciting inflammatory responses in the blood circulation." (PMID 38201587, 2023). "PLA2G2A expression is downregulated in 18 out of 31 types of cancer, indicating that it is generally downregulated in cancer." (PMID 36765904, 2023). "Specific inhibitors of PLA2G2A would be very useful to further evaluate its seemingly paradoxical roles in cancer development." (PMID 36233022, 2022). "By our studies we indicate that sPLA2-IIA is over-expressed in Paneth cells in adenomas comparative to malignant colorectal tumours, and its PLA2G2A gene is upregulated in human colon adenomas and is frequently subject of loss-of-heterozygosity (LOH)." (PMID 35198435, 2021). "The immune histochemical sections of the HPA database showed that the protein expression of SLPI, DES, IAPP, NPY, ISG15 and HLA-DMB in normal tissue was higher than that in cancer tissue, while the protein expression of PLA2G2A in normal tissue was lower than that in cancer tissue." (PMID 36774376, 2023). "Fourth, multiple microbial metabolites, which could influence immunity and cancer, are variably affected in the circulation and feces of Pla2g2a–/– mice." (PMID 35076024, 2022). "The important role of PLA2G2A in promoting cell survival and proliferation in K-ras-driven cancer cells suggests that it could be a potential therapeutic target." (PMID 36233022, 2022). "As such, inhibition of PLA2G2A could be a potential therapeutic strategy to suppress K-ras-driven cancer." (PMID 36233022, 2022). "Thus, further experiments using organ-on-a-chip models that mimic in vivo settings and animal studies are needed to further validate the therapeutic relevance of targeting PLA2G2A activity for cancer treatment." (PMID 36233022, 2022). "Among others, PLA2G2A is involved in arachidonic acid metabolism, antimicrobial activity, exocytosis of endocrine cells, the release of pro-inflammatory mediators, cell proliferation, and cancer." (PMID 35198435, 2021).
cancer (continued). "Upregulation of PLA2G2A in cancer cell significantly suppressed L. monocytogenes infection." (PMID 33408272, 2020). "Therefore, our study revealed that targeting PLA2G2A could provide a new potential therapeutic strategy to eliminate K-ras-driven PDAC cancer cells." (PMID 36233022, 2022). "However, the regulatory mechanisms of PLA2G2A expression in K-ras-driven cancer cells remain unknown." (PMID 36233022, 2022). "cPLA2α (PLA2G4A), iPLA2β (PLA2G6), sPLA2-IIA (PLA2G2A) and sPLA2-III (PLA2G3) are recognized to play a tumorigenic role in cancer." (PMID 38017485, 2023). "We validated significant overexpression of PLA2G2A across in situ GBCs, together with increased proliferation and cancer stemness in PLA2G2A-overexpressing GBC cells, indicating an important role for PLA2G2A during early carcinogenesis." (PMID 36198671, 2022). "The observed up-regulation in all three cancer nodules of FOXJ1 (13.75× in “A”, 18.51 in “B” and 20.39 in “C”) and PLA2G2A (6.68× in “A”, 18.75× in “B” and 23.61× in “C”) confirmed findings of other authors." (PMID 34209090, 2021). "Furthermore, the expression of QPCTL was positively correlated with SAA1, POSTN, PLA2G2A, SAA2,C6orf15, H19, PI3, etc., whose expression also affects cancer progress." (PMID 37063864, 2023). "Phospholipase PLA2G2A hydrolyzes cell membrane phospholipids and releases PUFA, which are then utilized by COX and CYP to produce eicosanoids that could promote cancer progression." (PMID 36233022, 2022). "In addition, PLA2G2A expression tended to be higher in the borderline between normal and carcinoma regions." (PMID 38201587, 2023). "Although there is currently no specific inhibitor of PLA2G2A for the clinical treatment of cancer, tanshinone I has been reported to inhibit PLA2G2A and could disrupt cellular PUFA metabolism for the synthesis of eicosanoids." (PMID 36233022, 2022).
cardiovascular disease (9 papers, 2008 to 2025). "Among secretory PLA2s, sPLA2-IIA, encoded by the PLA2G2A gene and also referred to as an inflammatory PLA2, has been associated with cardiovascular diseases." (PMID 36835616, 2023). "NPPA, NPPB and FRZB are recognized as biomarkers for HF,20, 21 and PLA2G2A is a biomarker for cardiovascular disease." (PMID 32638546, 2020). "It was reported that the occurrence of cardiovascular disease is closely related to PLA2G2A." (PMID 35126952, 2022).
infection (9 papers, 2007 to 2023). The state of being infected such as from the introduction of a foreign agent such as serum, vaccine, antigenic substance or organism. "When looking at the overall trend in protein expression over the whole time-course, PLA2G4A and PLA2G2A appear to share the same expression profile with a clear increase at 24 h post-infection." (PMID 32575076, 2020). "A strong impact of antimicrobials induced by Stat3 activation on the gut flora is also supported by our study as unlike control mice, C. rodentium sensitive Stat3ΔIEC mice showed no induction of RegIIIγ, RegIIIβ and Pla2g2a after infection." (PMID 25799189, 2015).
bacterial infection (4 papers, 2012 to 2023). "Enrichment analysis showed that SPINK1+ HCC and APOA1+SPINK1+PLA2G2A+ HCC cells were significantly involved in bacterial infection-related pathways." (PMID 37333982, 2023). "On the other hand, VCAM1, PLA2G2A and PLA2G10, down-regulated genes, maintain, amongst other functions, close relationships with the defensive host response in the face of bacterial infection, inflammation and immune response regulation/suppression situations." (PMID 32764374, 2020).
metabolic disease (4 papers, 2019 to 2025). A congenital disorder (due to inherited enzyme abnormality) or acquired (due to failure of a metabolically important organ) disorder resulting from an abnormal metabolic process. "PLA2G2A (secretory phospholipase A2 group IIA) was the most significant upregulated gene (fold change 3.9; adjusted P = 1.43E− 20), which is of particular interest to metabolic diseases in the context of atherogenesis, hepatic cholesterol metabolism and insulin sensitivity." (PMID 31664995, 2019).
intestinal diseases (1 paper, 2023). "PLA2G2A, the negative regulator of ferroptosis, can act as a modulator of gut microbiota, and gut microbes can affect intestinal diseases through the Hippo pathway." (PMID 38130953, 2023).
PLA2G2A also shares sentences with these, for which no sentence is quoted: myonecrosis (12 papers); asthma (4); neurodegenerative disease (4); rheumatoid arthritis (4); acute kidney injury (2); breast adenocarcinoma (2); coagulopathy (2); dementia (2); gastric adenocarcinoma (2); glaucoma (2); glioblastoma (2); hemorrhage (2); Insulin resistance (2); intestinal tumors (2); pancreatic ductal adenocarcinoma (2); acute coronary syndrome (1); acute leukemia (1); adenocarcinoma (1); adrenal tumor (1); age (1); ankylosing spondylitis (1); autoimmune myocarditis (1); bleeding disorders (1); Cerebral ischemia (1); chronic thromboembolic pulmonary hypertension (1); Crohn disease (1); dermatitis (1); diabetic retinopathy (1); dilated cardiomyopathy (1); enteritis (1).
A further 39 diseases each share a sentence with PLA2G2A in 1 paper.